RAD52 (RAD52 DNA repair protein)
Diseases named in the same sentence as RAD52 in open-access papers (continued):
Sharing a sentence is not in itself a finding about the gene and the disease.
ovarian carcinoma (17 papers, 2010 to 2025). A malignant neoplasm originating from the surface ovarian epithelium. "Collectively, our findings establish RAD52 as a promising therapeutic target to overcome PARP inhibitor resistance in BRCA2 -mutated ovarian cancer and offer mechanistic insights to inform future clinical strategies." (PMID 41040355, 2025). "BRCA mutation, one of the most common types of mutations in breast and ovarian cancer, has been suggested to be synthetically lethal with depletion of RAD52." (PMID 33922657, 2021). "We investigated the association of the RAD52 S346X variant as a modifier of the risk of developing breast and ovarian cancers in BRCA1 and BRCA2 mutation carriers from the Consortium of Investigators of Modifiers of BRCA1/2." (PMID 32175645, 2020). "Association of RAD52 S346X and risk of developing breast or ovarian cancer for BRCA1 and BRCA2 carriers." (PMID 32175645, 2020). "Because hRAD52 and BRCA2 play distinct roles in DSB repair, we examined the ability of the RAD52 S346X truncation variant to act as a modifier of susceptibility to breast and ovarian cancers in BRCA1 and BRCA2 mutation carriers." (PMID 32175645, 2020). "We tested the association of RAD52 S346X with risk of developing breast or ovarian cancer in a large cohort of BRCA1 and BRCA2 mutation carriers." (PMID 32175645, 2020). "While our findings suggest that SYCP2-mediated TC-HR operates independently of RAD52 in ovarian cancer, the potential cooperation between these ABL1 substrates—especially under stress conditions—merits further investigation." (PMID 40918650, 2025). "SF3B4 is a core splicing factor and our research showed that SF3B4 promotes ovarian cancer progression by improving the splicing efficiency of RAD52." (PMID 38317200, 2024). "SF3B is a component of the U2 small nuclear ribonucleoprotein (snRNP), known to control AS in renal cancer and SF3B4 in ovarian cancer by regulating AS of RAD52." (PMID 37091785, 2023). "Studies have shown that SF3B1, SF3B2, and SF3B3 can regulate target gene expression by alternative splicing to promote cancer progression, also SF3B3 controls AS in renal cancer and SF3B4 in ovarian cancer by regulating AS of RAD52." (PMID 37091785, 2023). "These compounds inhibited not only RAD52, but also the growth of BRCA1/2-deficient cells, typical for hereditary breast and ovarian cancers." (PMID 33671579, 2021). "When combined with mutations in genes that cause hereditary breast and ovarian cancer such as BRCA1, BRCA2, PALB2 and RAD51C, depletion of Rad52 is shown to be synthetically lethal." (PMID 28722656, 2017). "In the GBM data, the involved pathways include parts of the RB signaling and RTK signaling pathways (CDKN2B, CDK4; EGFR, NF1 ), and in the ovarian carcinoma data a recurrent mutated module related to cell cycle and DNA repair (CCNE1, MYC, RAD52 ) is revealed." (PMID 24565034, 2013). "For example, CDKN2B and CDK4 as well as EGFR and NF1 are involved in the RB and RTK signaling pathways, respectively and the CCNE1, MYC and RAD52 module in ovarian carcinoma is involved in cell cycle." (PMID 24565034, 2013). "Interestingly, the PE01 ovarian cancer cell line was more sensitive to mitoxantrone treatment showing a dramatic reduction in RAD52 protein and a substantial increase in DNA damage, relative to the other cell lines." (PMID 33784323, 2021). "Inhibition of RAD52 (RAD52 Homolog, DNA Repair Protein), the master regulator of SSA, results in decreased proliferation of BRCA1/2 (BRCA1/2 DNA Repair Associated)-deficient cells, occurring in many hereditary breast and ovarian cancer cases." (PMID 33671579, 2021). "In this review, we focus on the Rad52 activities and functions in HR and the possibility of using human RAD52 as therapeutic target in BRCA1 and BRCA2-deficient familial breast cancer and ovarian cancer." (PMID 27649245, 2016).
ovarian carcinoma (continued). "There is a significant effort to create small molecular inhibitors of RAD52 in order to clinically treat BRCA1 and BRCA2 mutant breast and ovarian cancers." (PMID 29145865, 2017). "New findings that RAD52 is essential for cell viability in BRCA1-, PALB2- and BRCA2- and RAD51 paralog-deficient cells, but not in normal cells, suggested that RAD52 may represent an attractive therapeutic target for killing hereditary breast cancer and ovarian cancer cells." (PMID 27649245, 2016).
leukemia (12 papers, 2017 to 2024). A malignant (clonal) hematologic disorder, involving hematopoietic stem cells and characterized by the presence of primitive or atypical myeloid or lymphoid cells in the bone marrow and the blood. "Both AICAR and AMP inhibited RAD52 nuclear foci formation in BRCA-1-deficient leukemia cells after cisplatin-induced DNA damage." (PMID 36980703, 2023). "A previous study confirmed that BRCA1/2-deficient leukemia cells were inhibited by the RAD52 inhibitor F79, which interferes with the DNA binding of RAD52." (PMID 33922657, 2021). "The mechanism behind its remarkably enhanced cytotoxicity is that chloram-HDi not only causes a significant DNA damage of leukaemia cells but also downregulates DNA repair protein, Rad52, resulting in the escalation of its DNA-damaging effect." (PMID 32314611, 2020). "Rad52-/-Parp1-/- mice are normal but show delay in the appearance of BRCA1-deficient leukemia when compared to single knockout mice." (PMID 31615159, 2019). "In 2013, the first paper was published that confirmed the successful inhibition of RAD52 in human BRCA1/2-deficient leukemia cells derived from patients." (PMID 31615159, 2019). "Similarly, targeting RAD52 has been demonstrated as a logical personalised synthetic lethal strategy in a range of FTK driven leukaemia types with associated impaired BRCA1/2." (PMID 38943005, 2024). "Similarly, the simultaneous inhibition of Polθ with PARP1 or RAD52 was performed in a study on HR-deficient leukemias and showed a strengthened antileukemia effect, in comparison to the separate use of Polθi." (PMID 39273083, 2024). "Therefore, depending on RAD52 to repair the increased damage levels in the leukemia stem environment caused ROS’ presence." (PMID 31652722, 2019). "Some studies have demonstrated that personalized synthetic lethality induced by targeting RAD52 is achieved in BRCA-deficient carcinomas and leukemias, while normal cells and tissues remain unaffected." (PMID 31652722, 2019). "This way, the use of a small peptide aptamer allows the target of one of the two DNA binding domains of RAD52 and, consequently, inhibits its DNA binding capacity, promoting the accumulation of deleterious DBSs in leukemia cells." (PMID 31652722, 2019). "BCR-ABL1- mediated leukemia, which is deficient in BRCA-controlled DNA repair, specifically relies on RAD52 to repair increased levels of damage in the leukemia stem cell environment due to enhanced ROS-induced damage." (PMID 28722656, 2017). "In addition, ABL1 kinase phosphorylates and regulates the activity of two DNA repair enzymes, PARP1 and RAD52, inhibition of which triggered synthetic lethality in BRCA1/2-deficient leukemia cells." (PMID 36959186, 2023). "Furthermore, due to cells oncogenic dependence on DNA repair by RAD52, this inhibition of RAD52′s DNA binding can lead to the suppression of the clonogenic and proliferative potential of leukemia progenitor and stem cells." (PMID 31652722, 2019). "Consequently, hindering the binding capability of RAD52 prohibited the proliferative and clonogenic potential of CML-CP leukemia stem and progenitor cells due to the cells’ oncogenic addiction to Rad52 DNA repair." (PMID 28722656, 2017). "Thus, by inhibiting the binding of RAD52 to DNA through targeting one of its two DNA binding domains using a small peptide aptamer, a deadly level of DSBs accumulate in malignant leukemia cells." (PMID 28722656, 2017). "Additional studies on constitutively active oncogenic BCR-ABL1 kinase have demonstrated that RAD52 phosphorylation facilitates its nuclear localization and stimulates SSA repair in leukemia cells." (PMID 36980703, 2023). "Constitutively active oncogenic BCR-ABL1 kinase facilitates nuclear localization of RAD52 and stimulates SSA repair in leukemia cells." (PMID 31615159, 2019). "These screens in HAP1 cells, a near-haploid leukemia-derived cell line, did not identify RAD52 as a synthetic lethal interactor." (PMID 39561207, 2024).
lung carcinoma (11 papers, 2015 to 2023). "It is worth mentioning that rs3748523 of the RAD52 gene is associated with lung cancer in low smokers of a young age." (PMID 36899086, 2023). "Our data found a significant association of rs3748523 of RAD52 with an increased risk of lung cancer, implicating collinearity in the studies for gene function in lung cancer." (PMID 36899086, 2023). "This preliminary study designated variation in RAD52 as a risk factor for squamous cell lung cancer by comparing 5,355 European ever-smoker lung cancer patients with 4,344 smoking control subjects." (PMID 28722656, 2017). "The authors showed that overexpression of RAD52 causes an increase in cell proliferation and that depletion of Rad52 in mouse lung cancer cells leads to cell death." (PMID 26610585, 2015). "Genome wide association studies (GWAS) have implicated the rs10849605 genetic variant at 12p13.33, the locus that encompasses RAD52 in the human genome, to be associated with a modest, but statistically significant, increased risk of lung cancer." (PMID 25793373, 2015). "We next undertook in-silico analysis of the rs10849605 variant and the RAD52/12p13.33 locus in the head and neck and lung cancers genomically characterised by the Cancer Genome Atlas (TCGA)." (PMID 25793373, 2015). "Genome-wide study has lately characterized RAD52 as a lung cancer susceptibility gene, the region containing RAD52 gene was amplified in patients affected by lung cancer." (PMID 26610585, 2015). "Interestingly, rs3764821 of ALDH3B1 and rs3748523 of RAD52 were associated with lung cancer in tobacco and betel quid chewers." (PMID 36899086, 2023). "The variant rs3748523 (RAD52) was found to be significantly associated with lower OS (CC vs. CG + GG: hazard ratio [HR] = 2.32; 95% CI = 1.24–4.31; p = 0.008) in lung cancer patients of later stages (stage III and stage IV) adjusted for age, sex and pack-years of smoking." (PMID 36899086, 2023). "Moreover, according to the GWAS results, the SNPs of RAD52 gene were associated with increased risk of lung cancer, particularly the development of lung squamous cell carcinoma." (PMID 34938740, 2021). "Furthermore, genetic variants in the HR genes BRCA2 and RAD52 have been liked to lung cancer susceptibility." (PMID 33203852, 2020). "Unadjusted logistic regression revealed strong association of rs3764821 of ALDH3B1 (G vs. A: OR = 2.64, 95% CI = 1.63–4.29, p = 0.00009***) and rs3748523 of RAD52 (G vs. C: OR = 1.69, 95% CI = 1.17–2.47, p = 0.006**) with lung cancer in additive model." (PMID 36899086, 2023). "This study focuses on lung cancer progression and how the DNA repair gene, Rad52, enables tumor cells to have sufficient genome integrity, i.e., the ability to repair lethal DNA damage, to avoid cell death." (PMID 28415565, 2017). "In accordance, several groups have begun identifying and optimizing small molecule inhibitors against proteins which are believed to enhance tumorigenesis, such as RAD52, to better treat lung cancers and other diseases." (PMID 28722656, 2017). "These genetic observations, thus, guided our group to functionally demonstrate that over-expression of RAD52 in lung cancer cell lines led to an increased rate of cell proliferation." (PMID 28722656, 2017). "Furthermore, we observed a poor response and decreased OS of the lung cancer patients with the variants rs3764821 (ALDH3B1) and rs3748523 (RAD52) for both first- and second-line chemotherapy." (PMID 36899086, 2023). "For instance, cisplatin induces the expression of the TLS polymerase REV3 in lung cancer cell lines leading to cisplatin resistance, while cisplatin-resistant lung cancer cells show significant upregulation of the DSB repair genes RAD51, RAD52, and CHK2." (PMID 36980782, 2023).
lung carcinoma (continued). "In this study, we also investigated the correlations between 35 polymorphisms in 9 DNA repair genes (XRCC3, BRCA2/ZAR1L, XPC, RAD52, MAD2L2, NFKB1, NFKBIA, TNFRSF1A, and FASN) with platinum-based chemotherapy prognosis in 399 patients with lung cancer." (PMID 35899106, 2022). "Increasingly, immunotherapies are coming to the forefront of lung cancer therapy as both monotherapies and combination therapies and our data suggest that the increased cell death found in NTCU-treated Rad52−/− mouse lungs may be due to an altered immune response." (PMID 28415565, 2017).
lung squamous cell carcinoma (6 papers, 2015 to 2023). "Our data provides support for the notion of RAD52 as a potential oncogene, implicating a major role for the combined processes of recombinational repair and host immunity in determining risk for Squamous Cell Lung Carcinoma (LUSC)." (PMID 28415565, 2017). "Along these lines, our own unpublished data shows that depletion of RAD52 in human squamous cell lung carcinoma cell lines enhances phenotypes associated with decreased tumorigenesis and increased cell death." (PMID 28722656, 2017). "Genetic variants located within the 12p13.33/RAD52 locus have been associated with lung squamous cell carcinoma (LUSC)." (PMID 25793373, 2015). "Concomitantly, unpublished data from our group suggests Rad52−/− mice are more resistant to squamous cell lung carcinoma compared to wildtype." (PMID 28722656, 2017). "Our studies focus on the role Rad52 plays in the progression of pre-malignancy to squamous cell carcinoma of the lung." (PMID 28415565, 2017). "RAD52 knockdown obviously weakens cell proliferation in lung squamous cell carcinoma." (PMID 35210412, 2022). "RAD52, a protein important for DNA double-strand break repair in homologous recombination, was first associated with NSCLC risk through a Genome-wide association study conducted in Europeans which linked the 12p13.33 locus containing RAD52 with squamous cell lung cancer risk." (PMID 28415565, 2017).
pancreatic cancer (6 papers, 2012 to 2025). "Pancreatic cancer showed an exceptionally high biallelic loss in HRR genes, with BRCA1, CDK12, FANCC, PPP2R2 A, RAD51 C, RAD51D, RAD52, WRN, and XRCC3 all presenting 100% biallelic loss." (PMID 40420266, 2025). "To evaluate the efficacy of the newly identified putative RAD52 inhibitors, we first treated patient-derived BRCA2-proficient (BxPC3) and BRCA2-deficient (Capan-1) pancreatic cancer cells." (PMID 33995041, 2021). "Similarly, RAD521–209 expression rescued the viability in BRCA2−/− CAPAN-1 pancreatic cancer cells, which was reduced approximately 4-fold by treatment with RAD52 shRNA." (PMID 33275133, 2020).
acute myeloid leukemia (4 papers, 2017 to 2025). Acute myeloid leukemia (AML) is a group of neoplasms arising from precursor cells committed to the myeloid cell-line differentiation. "In summary, our study have found miR-302a enhance the sensitivity of acute myeloid leukemia cell lines to VP-16 by targeting Rad52 and in part via the AKT/Gsk-3β/β-catenin signaling cascade." (PMID 29088754, 2017). "The synthetically lethal relationship between RAD52 and BRCA was first exploited using an oligopeptide aptamer to inhibit RAD52 in BRCA-downregulated acute myeloid leukemia cells." (PMID 34887904, 2021).
Fanconi anemia (4 papers, 2015 to 2024). Fanconi anemia (FA) is a hereditary DNA repair disorder characterized by progressive pancytopenia with bone marrow failure, variable congenital malformations and predisposition to develop hematological or solid tumors. "This pathway involves multiple proteins, including BRCA1, BRCA2, proteins of the MRN complex, CtIP, RAD51, ATM, H2AX, PALB2, RPA, RAD52, and proteins of the Fanconi anemia pathway." (PMID 38236558, 2024).
hepatocellular carcinoma (4 papers, 2019 to 2025). A malignant tumor that arises from hepatocytes. "Collectively, our findings establish succinylation as a master regulatory switch governing homologous recombination fidelity in hepatocellular carcinoma through PTM-directed control of RAD52 splicing." (PMID 41198615, 2025). "In particular, a direct correlation between specific RAD52 single-nucleotide polymorphisms (SNP) and tumorigenic risk was speculated, for instance in hepatitis B virus (HBV)—hepatocellular carcinoma (HCC) and in colorectal cancer." (PMID 36980703, 2023). "However, little is known about the impact of RAD52 on hepatocellular carcinoma (HCC)." (PMID 31719794, 2019).